LEP (leptin)
Diseases named in the same sentence as LEP in open-access papers (continued):
Sharing a sentence is not in itself a finding about the gene and the disease.
Obesity (continued). "Additionally, individuals with obesity also presented increased quantities of insulin, leptin, and HOMA‐IR and lower levels of METs compared to normal weight subjects." (PMID 31968396, 2020). "It is reported that obesity and overweight can lead to a high level of serum leptin, which may because that obesity always accompanies with insulin resistance and hyperinsulinemia, and insulin further enhance the expression of leptin." (PMID 32819324, 2020). "However, Treg cells are decreased in diet-induced obesity, which is consistent with the role of leptin in inhibiting Treg cell proportions, given that leptin levels are elevated in this setting." (PMID 33584724, 2020). "Children with mutations in genes encoding leptin or leptin receptors develop childhood monogenic obesity with higher BMI than age-matched, obese children without leptin deficiency." (PMID 33114326, 2020). "It is thus possible that leptin, which is typically elevated in individuals with obesity, could augment the IL-1RA levels in these participants." (PMID 32027700, 2020). "On the other hand, obesity is also characterized by metabolic (i.e., insulin resistance and decreased glucose tolerance) and endocrine (elevated cortisol levels but increased leptin and decreased ghrelin levels) alterations in the same domains of sleep disorders." (PMID 32050677, 2020). "Cross-sectional and prospective studies have observed an association between leptin concentrations and MetS independent of obesity." (PMID 33374992, 2020). "Additionally, various studies have demonstrated that probiotic and prebiotic supplementation improves glycemic parameters and leptin concentrations in patients affect by obesity, diabetes, and non-alcoholic fatty liver disease (NAFLD)." (PMID 33171610, 2020). "However, to date, no reports have focused on the effect of hesperidin on obese gene product i.e. leptin in comparison to already approved anti-obesity drug in hyperlipidemic and hyperglycemic conditions." (PMID 31929574, 2020). "The leptin’s inhibiting action on food intake has been ascribed to fat stores and obesity." (PMID 32183843, 2020). "Increased leptin levels in obesity may promote infection by lowering anti-viral type 1 IFN through the activation of suppressor of cytokine signaling-3 (SOCS-3) expression." (PMID 33123087, 2020). "However, in contrast to patients with obesity-associated NAFLD, patients with lipodystrophy have low levels of adipokines, including leptin, and leptin therapy thus appears to be highly effective for NASH in hypoleptinemic lipodystrophic patients." (PMID 33167521, 2020). "Similar to those of leptin, the mechanisms of ghrelin resistance in obesity are unclear." (PMID 32230732, 2020). "Moreover, TNFR1 had an adequate response to leptin generation and obesity establishment in mice fed a high-fat diet, and knockout of TNFR1 protected genetically obese ob/ob mice from insulin resistance." (PMID 32685099, 2020). "Additionally, leptin have been suggested as part of the mechanisms involved in the development of obesity-related carcinogenesis in pancreatic, prostate and colorectal cancer." (PMID 32824322, 2020). "Recently, the relationship between obesity, vitamin D, and leptin was investigated." (PMID 32528735, 2020). "In our previous studies of DNAJC27 in the context of obesity and T2D, we demonstrated a positive association between DNAJC27 and the common obesity biomarkers leptin and resistin, and also that DNAJC27 levels were elevated in PBMCs, plasma, and adipose tissue from individuals with obesity and T2D." (PMID 32733386, 2020). "The hypothalamus is the main area in which leptin’s anti-obesity effects are mediated." (PMID 32069871, 2020). "In obesity, propolis has also shown benefits, with in vitro and animal models providing evidence that it induces the transcription of adiponectin and leptin, reduces the mass of visceral adipose tissue, and regulates the levels of triglycerides, non-esterified fatty acids, and cholesterol." (PMID 33383693, 2020).
Obesity (continued). "In this context, leptin and PI3K can be involved in the obesity–colorectal cancer association: leptin activates PI3K in the colon cancer cells HCT-116 and could regulate the proliferation of colorectal carcinoma through the PI3K signalling pathway." (PMID 31936857, 2020). "An absence of leptin signalling due to genetic mutations in leptin or the leptin receptor leads to severe obesity from hyperphagia in both mice and humans, and restoration of signalling will reverse these effects." (PMID 33292104, 2020). "The authors suggested that impaired leptin signaling might have a protective role against diabetes- and obesity-induced IVD degeneration." (PMID 33396484, 2020). "Apart from regulating satiety, leptin has other body functions and has been proposed to be one of the major contributors to the increased sympathetic nervous system activity observed in obesity and obesity-induced cardiometabolic disturbances." (PMID 32756352, 2020). "Leptin is an important marker and may play a role in obesity, cardiovascular disease, inflammation, insulin resistance and diabetes mellitus type 2." (PMID 33489589, 2020). "In addition, leptin is produced by increased fat cells due to obesity, and it usually works in the hypothalamus to control the feeding center." (PMID 33102399, 2020). "In regard to NPY sexual dimorphism, lower levels of NPY found in female patients with obesity compared to male patients with obesity may be related to higher levels of leptin, inhibiting NPY production." (PMID 33644105, 2020). "As the prevalence of obesity and diabetes is continuously increasing, strategies are needed to develop and apply human cell-based models to better understand the precise role of leptin directly in different cardiac cell types and to overcome the existing translational barriers." (PMID 32655492, 2020). "Some studies also support the theory of an impact of leptin and leptin receptor genes polymorphism on AIWG, since mutations about these genes have been described to lead to obesity, hyperphagia and insulin resistance, as well as immune and reproductive disturbances." (PMID 32033608, 2020). "Here, we provide evidence the obesity-related leptin, whose circulating levels increase proportionally to total adipose tissue mass, may be a critical factor promoting malignant AIR growth in breast tissue." (PMID 32260113, 2020). "In obesity, adiposity positively correlates with leptin plasma levels." (PMID 32210914, 2020). "It is well established that obesity enhances the synthesis and release of leptin and, as anticipated, leptin concentrations were significantly higher in overweight participants compared to normal weight participants (overweight: 29.49 ng/mL; normal weight: 10.26 ng/mL; p < 0.001; SED: 2.04)." (PMID 33266325, 2020). "Leptin was positively associated with the neonatal length and skinfold thickness among women with obesity and inversely among women without obesity." (PMID 32635306, 2020). "While in mice, mutations of the ob gene determines obesity, infertility, diabetes and hypothermia, in humans, the installation of obesity is not related to a lack of functional leptin, but rather leptin resistance (ob mutations are very rare in humans)." (PMID 32354024, 2020). "This animal model of obesity appeared independent of leptin deficiency or mutations within the leptin receptor, and therefore does not replicate ob/ob or db/db mice." (PMID 35330637, 2020). "For instance, leptin and insulin typically rise with obesity and aging." (PMID 32499756, 2020). "The aim of this study was to evaluate the effects of an 8-week concurrent training program on markers of lipoinflammation (adiponectin, leptin, and adiponectin-leptin ratio) in 26 adult people with obesity, comparing the response to the training between men and women." (PMID 32854366, 2020).
Obesity (continued). "Indeed, it would have been interesting to also evaluate the evolution of the ghrelin and leptin levels, for instance, particularly since their respectively increase and decrease in response to similar weight loss interventions in adolescents with obesity could partly explain our results." (PMID 33353174, 2020). "Therefore, controlling obesity, improving IR and leptin resistance (LR), and delaying or reversing the occurrence of T2DM are major goals that need to be addressed urgently." (PMID 32920548, 2020). "Moreover, pro-inflammatory adipokines (resistin, fetuin-A, chemerin, leptin) are over-expressed in the adipocytes in obesity and adipokines with mainly anti-inflammatory effects (adiponektin, omentin) are supressed." (PMID 33092646, 2020). "Mechanistically, ROCK1 directly mediates leptin signaling and impairs ghrelin signaling through unknown mechanisms and the importance of these functions is underscored by obesity manifesting when hypothalamic ROCK1 function is impaired." (PMID 33633690, 2020). "Moreover, we examine the influence of obesity and perturbations in leptin signaling on the glia landscape in both the DVC and hypothalamus." (PMID 32152264, 2020). "Sleep disturbances can result in metabolic (decreased glucose tolerance and insulin sensitivity) and endocrine alterations such as decreased levels of leptin, increased evening concentrations of cortisol, increased levels of ghrelin and increased hunger and appetite (all of which promote obesity)." (PMID 32050677, 2020). "Additionally, dopamine and glutamate were positively correlated with neuroinflammatory cytokines (IL-12 and IL-6), leptin and BMI as markers of obesity, and cholesterol as an atherogenic marker." (PMID 33312720, 2020). "Obesity is associated with significant metabolic and endocrine abnormalities, including increased blood levels of growth factors such as insulin, insulin-like growth factor-1 (IGF-1) and leptin that can promote tumor cell growth and survival." (PMID 32549336, 2020). "Leptin has been shown to moderate obesity-related inflammation through mast cells." (PMID 32839413, 2020). "Taken altogether, in the current study, it was shown that leptin deficiency and leptin resistance shared some but not all metabolic changes in the development of obesity." (PMID 32585823, 2020). "Based on the evidence, the increased leptin, IGF-1, and sex hormone levels might be implicated in accelerated skeletal maturation in obesity." (PMID 32988365, 2020). "Leptin expression elevated significantly with the increase in obesity." (PMID 32181157, 2020). "Leptin has been described for its role in connecting obesity and cancer progression." (PMID 32518266, 2020). "Helicobacter pylori is an indicator for development of obesity; even though the exact pathophysiology is unknown, most studies correlate with gastrointestinal hormones such as leptin and ghrelin." (PMID 32566274, 2020). "Furthermore, given that the serum leptin concentration is strongly correlated with the amount of body fat mass and the BMI value, some scholars have proposed that obesity should be characterized by enhanced circulating leptin levels." (PMID 33597945, 2020). "Girls with obesity presented a hormonal profile characterized by increased levels of circulating insulin (p < 0.0001), leptin (p < 0.0001), c-peptide (p < 0.0001), amylin (p = 0.0018), glucagon (p = 0.0195), and glucagon-like peptide-1 (GLP-1, p = 0.0001), relative to eutrophic controls." (PMID 33644105, 2020). "The most known of adipocytokines is leptin, which plays a key role as a marker of obesity." (PMID 32570721, 2020). "Leptin is the hallmark of obesity and is a major appetite suppressant, although no effective obesity therapy based on this hormone has been developed till date." (PMID 33489589, 2020). "The systemic injection of SP could decrease the FFA, triglyceride, and leptin levels that are related to obesity from 2 weeks post the injection." (PMID 33028888, 2020).
Obesity (continued). "We used BMI and serum leptin for the analysis of obesity and fat mass effects." (PMID 33154737, 2020). "Moreover, metabolic disruptions in obesity can result in increased levels of cortisol, leptin, and insulin, leading to dysregulation of neuroendocrine networks and insulin resistance." (PMID 32102680, 2020). "Leptin resistance (impaired signaling) is present in obesity, producing hyperleptinemia." (PMID 32824322, 2020). "Importantly, it is suggested that insulin resistance, inflammation of the adipose tissue of the breast, elevated aromatase expression and elevated leptin levels play roles in the pathogenesis of obesity-related breast cancer." (PMID 33276660, 2020). "Contrary to leptin, circulating adiponectin levels are decreased in obesity and are inversely correlated with the body mass index (BMI), glycaemia, and circulating insulin levels, as well as with the risk of developing T2DM, obesity, and CVDs." (PMID 33081064, 2020). "Despite high circulating leptin levels, over-nutrition-induced obese mice show a reduced responsiveness to the appetite- and weight gain–suppressing effects of leptin, which is generally called leptin resistance and is a critical element in the development of obesity." (PMID 32560726, 2020). "As expected, the plasma levels of tumor necrosis factor α (TNFα) and leptin that were elevated in HFD-fed rats compared with those of normal rats in accord with a previous study showing that obesity and insulin resistance would increase the plasma level of proinflammatory cytokines and adipokines." (PMID 32098371, 2020). "Leptin treatment is effective to reduce body weight in animal models, but patients with obesity and associated hyperleptinemia do not respond well to leptin therapy." (PMID 33051459, 2020). "In obesity, hyperleptinemia can occur with accompanying leptin resistance in hypothalamic centres." (PMID 32443588, 2020). "Thus, leptin has attracted attention as a possible link between obesity and/or chronic inflammation and liver fibrosis." (PMID 32092909, 2020). "Hence, in the current work, we evaluated the hypolipidemic and anti-obesity effects of hesperidin in relation to its effects on leptin in serum and adipose tissues." (PMID 31929574, 2020). "Furthermore, leptin concentration is correlated with fat tissue amount and BMI, and, consequently, obesity is characterized by increased leptin levels." (PMID 33008429, 2020). "Moreover gestational hypoxia disrupts the neonatal leptin surge in such a way that hyperphagia and obesity are programmed for adult life." (PMID 32429235, 2020). "Thus, next we will focus on three relevant hormones that orchestrate energy balance and play a critical role in obesity: leptin, ghrelin, and insulin." (PMID 33105762, 2020). "The possible mechanisms involved in MSG-induced obesity may be the influence of MSG on energy balance by enhancing palatability through disrupting the hypothalamic signaling network of leptin action." (PMID 32489556, 2020). "Obesity did not promote significant metabolic and hemodynamic alterations, but this condition only caused elevation in leptin levels (Ob > C)." (PMID 32714085, 2020). "Following its discovery, leptin was immediately described as the anti-obesity miracle cure." (PMID 32069871, 2020). "The eCB/CB1R system is highly overactive during obesity, and both central and peripheral stimulations of this system have been suggested to contribute to the development of the metabolic syndrome, including leptin resistance." (PMID 33210603, 2020). "Instead, our data highlight the DVC as a critical and overlooked CNS cellular site-of-action that may be targeted for restoring leptin signaling in obesity." (PMID 32152264, 2020). "Adipokines such as leptin and other growth factors secreted on the background of obesity may influence cancer cell survival and solid tumor growth." (PMID 33381605, 2020).
Obesity (continued). "Over the years, research on the biological function of leptin has increased, showing great interest in the discovery of a possible treatment for obesity and other pathologies mainly related to the reduction of this hormone through combinations of biomolecules or the replacement of leptin." (PMID 33334030, 2020). "Data from these studies will provide supporting evidence, indicating that targeting the leptin signaling pathway in highly aggressive obesity-related cancers may be an effective means to improving the success of BC treatment." (PMID 32471192, 2020). "Thus, given the lowest amount of FM, the patients with AN showed the highest plasma levels of SIRT1 and adiponectin and the lowest concentration of leptin, while the opposite was found in the group of patients with obesity." (PMID 33202604, 2020). "In a brain-specific reduced ER stress mouse model, severe leptin resistance significantly increased obesity on a high-fat diet, which suggested that ER stress might participate in the adjustment of insulin sensitivity in brain." (PMID 32375323, 2020). "Such short sleep duration can lead to weight gain and eventual obesity, due to an increase in neuronal reward responses to unhealthy foods, potential alterations in hormonal activity (leptin, ghrelin, GLP-1, orexins), and the increased time awake that leads to higher caloric intake." (PMID 33585363, 2020). "In clinical obesity studies, curcumin intake improved a set of pivotal body composition parameters, including reducing body weight, body mass index (BMI), and waist circumference and modulating the adiponectin and leptin levels." (PMID 32992936, 2020). "Although the precise mechanism by which obesity causes MME remains unclear, obesity can lead to a rise in the concentration of leptin, which stimulates the expression of transforming growth factor-β1 (TGF-β1)." (PMID 32878271, 2020). "In obesity, leptin further decreases the secretion of adiponectin, an anti-inflammatory adipokine." (PMID 32650509, 2020). "Current studies have demonstrated that some antihypertensive medications may be more relevant than others in terms of reducing leptin levels in obesity." (PMID 33076921, 2020). "LEP has a role in acute and chronic inflammation via the regulation of cytokine expression and it contributes to the proinflammatory environment observed in obesity and psoriasis in humans." (PMID 33316917, 2020). "In obesity, leptin is increased, suggesting leptin resistance." (PMID 32154197, 2020). "Although the anti-obesity effects of PNS mediated by gut microbiota were associated with the leptin-induced thermogenic program, the impact of PNS on the obesity-related metabolic phenotype might be correlated with another leptin-independent mechanism." (PMID 33042284, 2020). "For infants who are overnourished in utero and born large, their hypothalamus is resistant to high levels of circulating leptin which reduces their satiety sensitivity and may also lead to obesity." (PMID 32435480, 2020). "One potential mechanism may involve sexually dimorphic changes in the central actions of insulin and leptin with obesity." (PMID 32160920, 2020). "It is also suggested that exercise training in women with obesity might influence the regulation of food intake via improved leptin sensitivity." (PMID 32729763, 2020). "Moreover, circulating molecules such as trimethylamine N-oxide (TMAO), endothelial microparticles (EMPs), and leptin, have been identified as biomarkers of vascular injury in obesity." (PMID 32802124, 2020). "Obesity status and female sex may exert modifying effects on LEP transcription, particularly in obese women." (PMID 31914480, 2020). "The fact that β3-integrin was only upregulated by low levels of leptin (0.01 nM) suggests that obesity, which induces higher levels of leptin, may be detrimental to uterine receptivity." (PMID 32906753, 2020).